CPLX2 (complexin 2)
Description:
Negatively regulates the formation of synaptic vesicle clustering at active zone to the presynaptic membrane in postmitotic neurons. Positively regulates a late step in exocytosis of various cytoplasmic vesicles, such as synaptic vesicles and other secretory vesicles. Also involved in mast cell exocytosis (By similarity).
Synonyms: CPX-2; DKFZp547D155; 921-L; CPX2; Hfb1
Tractability: PROTAC: its protein half-life has been measured.
Gene: Protein-coding gene on chromosome 5 (175,796,306 to 175,884,022, forward strand). Ensembl gene ENSG00000145920.
Subcellular location: Cytoplasm, cytosol; Presynapse; Nucleus; Perikaryon
Subcellular location (Human Protein Atlas): Vesicles
Gene Ontology:
Molecular function: protein binding; SNARE binding; calcium-dependent protein binding
Biological process: modulation of chemical synaptic transmission; positive regulation of synaptic plasticity; regulation of exocytosis; regulation of synaptic vesicle fusion to presynaptic active zone membrane; synaptic vesicle exocytosis; exocytosis; neurotransmitter transport
Cellular component: nucleus; perikaryon; presynapse; SNARE complex; synaptobrevin 2-SNAP-25-syntaxin-3-complexin complex; terminal bouton; calyx of Held; cytosol; dendrite; glutamatergic synapse; neuronal cell body; postsynapse; synapse; synaptobrevin 2-SNAP-25-syntaxin-1a-complexin II complex; vesicle tethering complex
Genetic constraint (gnomAD): Loss-of-function variants: 5 observed, 15.4 expected, observed/expected ratio (o/e) 0.32, 90% interval 0.17 to 0.68. The upper end of that interval is the gene's LOEUF score, 0.68, which puts it in group 2 of 6, group 1 being the genes least tolerant of losing a copy. Missense variants: 144 observed, 182.48 expected, observed/expected ratio (o/e) 0.79, 90% interval 0.69 to 0.91. Synonymous variants: 89 observed, 75.46 expected, observed/expected ratio (o/e) 1.18, 90% interval 0.99 to 1.41.
Homologues: Orthologues: chimpanzee CPLX2 (100% identical), guinea pig CPLX2 (100% identical), mouse Cplx2 (100% identical), rat Cplx2 (100% identical), pig CPLX2 (99% identical), tropical clawed frog cplx2 (97% identical), zebrafish cplx2b (94% identical), rabbit CPLX2 (80% identical), dog CPLX2 (51% identical), Drosophila melanogaster cpx (40% identical), Caenorhabditis elegans cpx-1 (32% identical), Caenorhabditis elegans cpx-2 (21% identical). Paralogues in human: CPLX1 (84% identical), CPLX4 (35% identical), CPLX3 (34% identical).
Diseases named in the same sentence as CPLX2 in open-access papers:
CPLX2 is named in the same sentence as 36 diseases in open-access papers, as found by Europe PMC text mining. Sharing a sentence is not in itself a finding about the gene and the disease. The quoted sentences say what the papers report.
schizophrenia (12 papers, 2005 to 2025). A major psychotic disorder characterized by abnormalities in the perception or expression of reality. "Decreased expression of Cplx2 is associated with schizophrenia and Huntington’s disease and with decreased neurotransmitter release." (PMID 34013450, 2021). "In this report, we present an association study of SYN2 and CPLX2 with schizophrenia using 12 polymorphisms in the Korean population." (PMID 16131404, 2005). "A similar situation was also observed with the positive association of the haplotype in CPLX2 with schizophrenia [CPLX2-1 – CPLX2-2, 0.852 vs. 0.412 (schizophrenics vs. controls)]." (PMID 16131404, 2005). "Only one pair of SNPs (CPLX2-1 vs. CPLX2-2) showed a significant haplotype association with schizophrenia (χ2 = 16.28, df = 3, P = 0.0009), even after the Bonferroni correction (n = 10, Pcorr = 0.009)." (PMID 16131404, 2005). "For the combination of CPLX2-1 – CPLX2-2, the G allele-the C allele haplotype was observed more frequently in the schizophrenia group than the control group." (PMID 16131404, 2005). "We found significant differences in the haplotype frequencies in both SYN2 and CPLX2 polymorphisms between schizophrenia and control groups." (PMID 16131404, 2005). "Based on their localization, well-established neurobiological roles, and expression patterns in schizophrenic patients, we selected SYN2 and CPLX2 as candidate genes for conferring susceptibility to schizophrenia." (PMID 16131404, 2005). "Genotype distributions and allele frequencies of each polymorphism of the SYN2 and CPLX2 in the schizophrenia and control groups." (PMID 16131404, 2005). "Cplx2-null mutant mice exhibit cognitive function loss in conjunction with a minor brain lesion, representing a relevant environmental risk (“second hit”) for schizophrenia." (PMID 38327830, 2024). "Decreased expressions of complexin 2 have also been associated with neurodegenerative diseases including Alzheimer’s, Huntington’s, and Parkinson’s; psychiatric disorders including schizophrenia and bipolar disorder, with seizures and epilepsy being common comorbidities." (PMID 32630817, 2020). "Our results suggest that both SYN2 and CPLX2 polymorphisms may contribute susceptibility to schizophrenia in the Korean population." (PMID 16131404, 2005). "A very recent study looking at the percentage reads of new isoforms identified new CPLX2 isoforms not only in patients with schizophrenia but also in patients with epilepsy." (PMID 40699779, 2025). "As an AD-selective DEG eliminated by CBD treatment, Cplx2 also modulates neuronal control of memory in patients with schizophrenia and during frontotemporal dementia (FTD) pathogenesis." (PMID 40979532, 2025). "Previous studies have reported that the protein and mRNA levels of the synapsin 2 (SYN2) and complexin 2 (CPLX2) genes were decreased in patients with schizophrenia." (PMID 16131404, 2005). "Six single nucleotide polymorphisms (SNPs) and one 5-bp insertion/deletion in SYN2 and five SNPs in CPLX2 were genotyped in 154 Korean patients with schizophrenia and 133 control patients using direct sequencing or restriction fragment length polymorphism analysis." (PMID 16131404, 2005). "In this study, we observed significant, pairwise haplotype associations with schizophrenia for two pairs of SNPs in SYN2 (SYN2-1 – SYN2-2 and SYN2-2 – SYN2-4; Pcorr = 9.35 × 10-5 and Pcorr = 0.019, respectively) and one pair of SNPs in CPLX2 (CPLX2-1 – CPLX2-2, Pcorr = 0.009)." (PMID 16131404, 2005). "For example, miR-153 regulates Snap25, Vamp2, Snca, Trak2, Bsn and Pclo genes at the mRNA level; miR-137 inhibits complexin-1, Nsf and Syt1 in mouse model of schizophrenia; miR-34c targets VAMP-2 and miR-135a binds the complexin-1 and complexin-2 genes in the amygdala." (PMID 32252776, 2020).
depression (6 papers, 2016 to 2025). "Rg1 (20 mg/kg) ameliorated memory impairment and depression-like behavior via downregulation of complexin-2 (CPLX2), synaptosomal-associated protein 25 (SNP25) and synapsin-2 (SYN2) expression in the hippocampus of mice." (PMID 35953850, 2022). "The present study showed that multiple pontine genes, including Anxa1, Serpinf1, Arrb1, Cplx2, Nrg1, and Psen1 were altered in a model of depression." (PMID 39135796, 2024). "As a cytosolic protein, a significant change of CPLX2 expression was observed in multiple neurological disorders such as depression." (PMID 29204248, 2017). "CPLX2 was a protein modulator of neurotransmitter release that was downregulated in patients suffering from depression." (PMID 29204248, 2017). "In our study, we found that the expression of CPLX2 was significantly decreased in 3xTg-AD mice compared with the WT mice and modulated by the treatment of Rg1, suggesting an involvement of CPLX2 in behavioral impairment of 3xTg-AD mice and the protective effects of Rg1 on memory and depression." (PMID 29204248, 2017). "Importantly, CPLX2, a depression- and memory-related protein, and SYN2 and SNP25, two memory-related proteins, were significantly downregulated in the hippocampus of 3xTg-AD mice, while the expression of these proteins was significantly modulated by the treatment of Rg1 treatment." (PMID 29204248, 2017).
cognitive disorder (5 papers, 2015 to 2024). A disease affects cognitive processes. "Besides, CPLX-2 knockout mice displayed cognitive disorder and selective impairment in long-term potentiation (LTP)." (PMID 29204248, 2017). "Furthermore, complexin-2 knockout mice show prominent cognitive impairment." (PMID 29593495, 2018). "Taken together, our finding indicated that loganin prevented cognitive impairment related with the increased expression of SYN2 and Cplx2 that were involved in the regulation of synaptic dysfunction." (PMID 34689137, 2021).
cognitive decline (4 papers, 2017 to 2025). "Higher baseline levels of most proteins (SNAP-25, NfL, Ng, β-syn, γ-syn, AP2-complex subunit β [AP2], GDI-1, PEBP-1, all 14-3-3 proteins and CPLX2) were also associated with faster cognitive decline (interaction protein*time p < 0.05)." (PMID 39121126, 2024). "A study demonstrating the protection of 12 hippocampal proteins, including CPLX-1 and CPLX-2, reinforces the hypothesis that targeted interventions like CoQ10 may help mitigate the progression of cognitive decline associated with AD." (PMID 40944284, 2025).
memory impairment (3 papers, 2021 to 2024). "Rg1 can improve memory impairment and depression-like behavior in 3 × Tg-AD mice by upregulating the expression of the depression and memory-related proteins complexin-2 (CPLX2), synapsin-2 (SYN2), and synaptosomal-associated protein 25 (SNP25)." (PMID 34149431, 2021).
Anxiety (2 papers, 2021 to 2025). Intense feelings of nervousness, tension, or panic often arise in response to interpersonal stresses. "Our finding of altered Cplx2 expression indirectly corroborates a study on chronic mild stress that links Cplx2 to the anxiety-susceptible experimental rat group." (PMID 40699779, 2025).
glioblastoma (2 papers, 2022 to 2024). The most malignant astrocytic tumor (WHO grade IV). "A recent study has also shown that CPLX2 was up-regulated in glioblastoma multiforme tissue compared to normal brain tissue, serving as an effective marker." (PMID 36581948, 2022).
glioma (2 papers, 2017 to 2025). A benign or malignant brain and spinal cord tumor that arises from glial cells (astrocytes, oligodendrocytes, ependymal cells). "CPLX2 is a potential tumor suppressor and prognostic biomarker for glioma by modulating hypoxia and inflammation pathways." (PMID 41008963, 2025).
Huntington disease (2 papers, 2012 to 2021). Huntington disease (HD) is a rare neurodegenerative disorder of the central nervous system characterized by unwanted choreatic movements, behavioral and psychiatric disturbances and dementia. "Abnormal levels of CPLX2 have been implicated in Huntington's disease, while its levels are reduced in AD." (PMID 22558197, 2012).
autoimmune disease (1 paper, 2019). A disorder resulting from loss of function or tissue destruction of an organ or multiple organs, arising from humoral or cellular immune responses of the individual to their own tissue constituents. "Further exploration of the molecular mechanism regulating spontaneous vesicle fusion by CPLX2 may lead to an understanding of diseases caused by abnormal secretion of antibodies, such as autoimmune diseases." (PMID 31691534, 2019).
infantile spasms (1 paper, 2025). A rare epilepsy syndrome characterized by onset of epileptic spasms in infants between 2 and 12 months of age, and rarely up to 24 months. "Interestingly, two down-regulated genes in males, Atp2a2 and Cplx2, were up-regulated in females, indicating opposite effects of triggering the infantile spasms in the two sexes." (PMID 40699779, 2025).
keratoconus (1 paper, 2020). A degenerative, structural disorder of the eye, characterized by a cone-shaped protrusion of the cornea. "Through WDD, we identified SMAD3 as an additional keratoconus-susceptibility gene (OR = 1.44 (1.16–1.80), P = 0.001), and CPLX2 as a future candidate gene for keratoconus-susceptibility (OR = 0.70 (0.46–1.05), P = 0.082)." (PMID 32737415, 2020). "Specifically, we selected seven keratoconus-susceptibility genes (CDH13, SMAD3, ADAM12, CSMD1, NRXN1, CPLX2, and WWOX) for further analysis." (PMID 32737415, 2020). "CPLX2 rs4242187 tended to show an association with keratoconus, but the association was not statistically significant (OR (95% CI) = 0.70 (0.46–1.05), P = 0.082)." (PMID 32737415, 2020). "Although CPLX2 (ranked number 16 by Watson) showed a marginally significant association with keratoconus, only SMAD3 (with the highest similarity score) showed a robust association with keratoconus." (PMID 32737415, 2020).
lung carcinoma (1 paper, 2022). "It has been reported that CPLX2 could be a reasonable biomarker in high-grade lung cancer." (PMID 35955705, 2022).
osteoporosis (1 paper, 2023). A condition of reduced bone mass, with decreased cortical thickness and a decrease in the number and size of the trabeculae of cancellous bone (but normal chemical composition), resulting in increased fracture incidence. "While this pathway has also appeared in analyses of differentially expressed genes in post-menopausal osteoporosis, roles of specific differential genes, such as Cplx2, Cacna1b, and Dnm1, have not been investigated." (PMID 36788807, 2023).
synovitis (1 paper, 2025). Inflammation of a synovial membrane. "In conclusion, this study demonstrates that OPM alleviates KOA-associated nociceptive hypersensitivity and synovitis by targeting CPLX2-mediated trafficking dynamics of transient receptor potentials in DRG neurons." (PMID 41194174, 2025).
tumor (4 papers, 2022 to 2025). "We found that the expressions of CCL1, FABP7, S100B, CTSW, and SEZ6 significantly decreased in the tumor tissue, the expression of CPLX2 and SPIB increased obviously in BC." (PMID 36581948, 2022). "We did however confirm that levels of CPLX2 were significantly lower in the metastasis-derived VIVA1-43Spl cell line compared to the primary tumour-derived VIVA1-43LIG cell line derived from the same animal supporting a role for its downregulation in association with metastasis." (PMID 35318435, 2022).
cancer (2 papers, 2025). A tumor composed of atypical neoplastic, often pleomorphic cells that invade other tissues. "CPLX2 and ELAVL3 were significantly downregulated in MSC lines compared to cancer cell lines." (PMID 39621192, 2025).
psychiatric diseases (2 papers, 2014 to 2020). "Concerning psychiatric diseases, a SNP (rs3822674) in the complexin 2 gene (CPLX2), associated with altered cognition in SCZ subjects, was described to affect miR-498 binding and gene expression." (PMID 24653674, 2014).
CPLX2 also shares sentences with these, for which no sentence is quoted: epilepsy (3 papers); lung neuroendocrine tumors (3); Parkinson disease (3); breast carcinoma (2); attention deficit-hyperactivity disorder (1); bipolar disorder (1); bronchial hyperreactivity (1); colorectal cancer (1); cortical atrophy (1); esophageal cancer (1); frontotemporal dementia (1); infection (1); lymphoma (1); neurodegenerative disease (1); neurological disorders (1); Parkinson’s (1); R6 (1); synucleinopathy (1).